ACO2 (aconitase 2)
Diseases named in the same sentence as ACO2 in open-access papers (continued):
Sharing a sentence is not in itself a finding about the gene and the disease.
Metabolic Disorders (3 papers, 2020 to 2025). "To date, a number of families or isolated patients with mutations in the Aconitase 2 (ACO2) gene were described, clinically presenting with neurodegenerative or metabolic disease of variable severity." (PMID 33028849, 2020).
neuromuscular disease (1 paper, 2021). "Interestingly, mtDNA depletion has been observed in patients’ fibroblasts carrying a heterozygous ACO2 mutation leading to haploinsufficiency, congruent with another case of recessive neuromuscular disease due to compound heterozygous mutations in ACO2." (PMID 33806088, 2021).
ACO2 also shares sentences with these, for which no sentence is quoted: Cerebellar atrophy (4 papers); autosomal dominant optic atrophy (2); cardiomyopathy (2); Cerebral atrophy (2); cortical atrophy (2); epilepsy (2); ovarian carcinoma (2); acute myocardial infarction (1); Astigmatism (1); biotinidase deficiency (1); cerebellar ataxia (1); depression (1); developmental delay (1); dilated cardiomyopathy (1); Dystonia (1); epilepsy syndrome (1); female reproductive system tumors (1); fungal infection (1); fungal keratitis (1); Hartnup disease (1); head and neck squamous cell carcinoma (1); hearing (1); Hepatic steatosis (1); hepatocellular carcinoma (1); Hyperglycemia (1); kidney cancer (1); lung adenocarcinoma (1); mammary adenocarcinoma (1); maple syrup urine disease (1); movement disorder (1).
A further 9 diseases each share a sentence with ACO2 in 1 paper.